SMILR (smooth muscle induced lncRNA, enhancer of proliferation)
Gene: Long non-coding RNA gene on chromosome 8 (122,414,332 to 122,428,551, reverse strand). Ensembl gene ENSG00000255364.
Gene Ontology:
Biological process: positive regulation of gene expression; positive regulation of vascular associated smooth muscle cell proliferation
Cellular component: cytoplasm; extracellular region; nucleus
Diseases named in the same sentence as SMILR in open-access papers:
SMILR is named in the same sentence as 6 diseases in open-access papers, as found by Europe PMC text mining. Sharing a sentence is not in itself a finding about the gene and the disease. The quoted sentences say what the papers report.
atherosclerosis (5 papers, 2016 to 2024). A disease characterized by the build-up of fatty material and calcium deposition in the arterial wall resulting in partial or complete occlusion of the arterial lumen. "We also discovered that SMILR can be released from cells and is detectable in plasma from patients with enhanced inflammation and thus susceptibility to atherosclerosis." (PMID 27052414, 2016). "SMILR expression increases in both the cytoplasm and nucleus of VSMCs during phenotypic switching, subsequently leading to its release into the extracellular space, which allows for the detection of SMILR in plasma, making it a potential biomarker for patients at risk of atherosclerosis-related PAD." (PMID 39049097, 2024). "Collectively, these data suggest that the SMILR/CENPF-STAU1 axis is activated in unstable atherosclerosis." (PMID 31339449, 2019). "Moreover, SMILR was upregulated in unstable human atherosclerotic plaques and positively correlated with elevated levels of inflammatory C-reactive protein, suggesting that targeting SMILR may confer protection from atherosclerosis." (PMID 34234740, 2021). "Interestingly, we found a similar role for SMILR in HCASMCs and may, therefore, also be involved in atherosclerosis." (PMID 31339449, 2019).
cancer (1 paper, 2021). A tumor composed of atypical neoplastic, often pleomorphic cells that invade other tissues. "Survival analysis based on promoter methylation did identify four associated genes OR2S2, SMILR, RNU6-653P, and AC010543, although very little is known about their biologic function, and nothing is published related to cancer." (PMID 34112938, 2021).
cardiovascular diseases (1 paper, 2019). "The upregulation or downregulation of the SMILR-axis and its consequential effects on vSMC proliferation could influence numerous cardiovascular diseases." (PMID 31339449, 2019).
SMILR also shares sentences with these, for which no sentence is quoted: aneurysmal disease (1 paper); colorectal cancer (1); tumor (1).